SST (somatostatin)
Diseases named in the same sentence as SST in open-access papers (continued):
Sharing a sentence is not in itself a finding about the gene and the disease.
oropharynx cancer (1 paper, 2015). A primary or metastatic malignant neoplasm that affects the oropharynx. "Among patients with oral cavity and oropharynx cancer, the disease-free survival rate in the group of patients with both SST and SSTR1 methylation was 48.1% as compared with 81.4% in the other groups (log-rank test, P = 0.028)." (PMID 25734919, 2015). "Among patients with oral cavity and oropharynx cancer, methylation of both SST and SSTR1 promoters correlated with reduced disease-free survival (log-rank test, P = 0.028)." (PMID 25734919, 2015).
ovarian tumours (1 paper, 2002). "Increased expression of native somatostatin correlating with somatostatin receptors in malignant ovarian tumours raises the possibility that either synthetic somatostatin antagonists or receptor agonists may have therapeutic potential." (PMID 12085262, 2002).
pancreatic disease (1 paper, 2020). "In addition in settings of pancreatic disease and DEP, damage to δ cells and somatostatin may affect development of DM though influence on incretin hormone response." (PMID 33250773, 2020).
parathyroid carcinoma (1 paper, 2024). "Among PNENs in our cohort, there was no parathyroid carcinoma, so we could not obtain information on the [68Ga]-DOTA-peptides uptake and SST expression in parathyroid carcinoma." (PMID 39682626, 2024).
periodontal disease (1 paper, 2019). "Although the present study suggests a potential role of SSTR2 in the aetiopathogenesis of periodontal disease, we have not examined the actions of SST itself and the regulation of other SSTRs." (PMID 30609928, 2019). "Since SST has antiproliferative, antiangiogenetic, and proapoptotic effects, our findings suggest that SSTR2 might play a critical role in periodontal diseases." (PMID 30609928, 2019).
peripheral nerve injury (1 paper, 2014). Injury to a peripheral nerve. "Following peripheral nerve injury sst2A-like immunoreactivity (LI) was decreased, and SST-LI increased in DRGs." (PMID 24521084, 2014).
prion disease (1 paper, 2022). A transmissible disease that is caused by a protein that is able to induce abnormal folding of normal cellular proteins, leading to characteristic spongiform brain changes, which are associated with neuronal loss without an inflammatory response. "Bauer and colleagues report that among the six neuron types studied, somatostatin neurons have an unexpectedly strong and similar response to two distinct genetic prion diseases before disease onset." (PMID 36192034, 2022).
prolactinomas (1 paper, 2025). "In our series of 34 patients with prolactinomas, which is, to the best of our knowledge, the largest prolactinoma series for SST and D2R receptor immunohistochemical staining, 22 (64.7%) were DA-resistant and 4 (11.8%) intolerant to DA therapy." (PMID 41184667, 2025). "While a number of studies have evaluated the expression of SST and D2 receptors among prolactinomas, our study is unique in that it evaluated the expression of SST2, SST5 and D2R within a single cohort." (PMID 41184667, 2025).
protein deficiency (1 paper, 2023). "Interestingly, somatostatin (SST)-IR cells were also decreased in the IUGR rats, suggesting other impairments in the inhibitory circuitry induced by the intrauterine protein deficiency." (PMID 36720849, 2023).
rectal NETs (1 paper, 2025). "Likewise, NETs from other GI sites have their own attributes, e.g., the stomach has three distinct subtypes of NETs, duodenal NETs have a strong association with familial syndromes and/or gastrin/somatostatin secretion, and colonic and rectal NETs tend to be managed quite differently." (PMID 40361413, 2025).
respiratory depression (1 paper, 2023). A decrease in ventilation secondary to impaired signals from the central nervous system. "Using in situ hybridization, we first quantified the expression of Sst (gene encoding somatostatin) and Oprm1 (gene encoding MORs) mRNAs in brainstem regions involved in the control of breathing and respiratory depression." (PMID 37364996, 2023). "We examined the coexpression of Sst (gene encoding somatostatin) and Oprm1 (gene encoding MORs) mRNAs in brainstem regions involved in respiratory depression." (PMID 37364996, 2023). "Together these findings suggest that somatostatin-expressing cells are critical for normal respiration and are found within brainstem sites involved in the control of breathing and opioid-induced respiratory depression." (PMID 37364996, 2023). "Somatostatin is a major neuropeptide found within these brainstem circuits, but it is unknown whether somatostatin circuits regulate respiratory depression by opioids." (PMID 37364996, 2023). "Somatostatin is a major neuropeptide found in brainstem circuits regulating breathing, but it is unknown whether somatostatin-expressing circuits regulate respiratory depression by opioids." (PMID 37364996, 2023). "We hypothesized that somatostatin and MORs are coexpressed in respiratory circuits and that somatostatin-expressing cells contribute to the regulation of opioid-induced respiratory depression." (PMID 37364996, 2023). "Moreover, preBötC somatostatin-expressing cells project to the KF nucleus, both of which are involved in opioid-induced respiratory depression." (PMID 37364996, 2023).
respiratory failure (1 paper, 2025). The significant impairment of gas exchange within the lungs resulting in hypoxia, hypercarbia, or both, to the extent that organ tissue perfusion is severely compromised. "Neuropeptides like galanin, pituitary adenylate cyclase-activating peptide (PACAP), orexin, somatostatin, and bombesin-like peptides may modulate chemosensitivity and respiratory function, potentially exacerbating respiratory failure during seizures." (PMID 40004062, 2025).
retinal degeneration (1 paper, 2024). Degeneration of the retina. "Here, we investigated if changes in cortical functioning is linked to alterations in GABAergic population of neurons and its two important subsets, somatostatin (SST) and parvalbumin (PV) neuron in rd1 model of retinal degeneration (RD)." (PMID 39444393, 2024).
secreting pituitary adenoma (1 paper, 2020). "Initial management of GH‐secreting pituitary adenoma is widely accepted as endonasal trans‐sphenoidal surgery, with second‐line therapy where disease is uncontrolled in most cases being somatostatin analogue therapy." (PMID 32704572, 2020).
secretory diarrhoea (1 paper, 2025). "It illustrates that somatostatin analogues remain a viable treatment consideration for secretory diarrhoea even when the aetiology remains elusive." (PMID 41195063, 2025).
serous ovarian cancer (1 paper, 2023). "The results showed that the expression of SST and DEFB1 was higher in serous ovarian cancer tissues, while the expression of the other six genes was lower in tumor tissues." (PMID 37318692, 2023).
severe combined immunodeficiency (1 paper, 2018). Severe combined immunodeficiency (SCID) comprises a group of rare monogenic primary immunodeficiency disorders characterized by a lack of functional peripheral T lymphocytes resulting in early-onset severe respiratory infections and failure to thrive. "To further investigate whether the population of human SST and PV interneurons could be enriched in grafts, we transplanted 7-week hPSC-derived MGE progenitors into the ventral forebrain of neonatal severe combined immunodeficiency (SCID) mice." (PMID 30251953, 2018).
skin cancer (1 paper, 2011). "Of note, there is growing evidence that woundingpromotes epidermal tumorigenesis and several authors have hypothesized that “canceris an overhealing wound” which also points to a roleof SST agonists in the therapy of skin cancer." (PMID 21589940, 2011).
Skin rash (1 paper, 2022). A red eruption of the skin. "Long-acting somatostatin was used after surgery, and the skin rash did not recur." (PMID 35641533, 2022).
somatotrophinomas (1 paper, 2020). "This indicates that the predominant action of JQ1 is likely through apoptosis; however, somatostatin analogues that target somatostatin receptors are effective in the treatment of somatotrophinomas, a pituitary NET, although their efficacy in treating corticotrophinomas is limited." (PMID 31935194, 2020).
Tinnitus (1 paper, 2017). Tinnitus is an auditory perception that can be described as the experience of sound, in the ear or in the head, in the absence of external acoustic stimulation. "Pathological alterations in parvalbumin-positive interneurons and somatostatin-positive interneurons as well as subsequent multiple excitatory-inhibitory neural interactions may lead to the emergence and maintenance of tinnitus perception." (PMID 28053240, 2017).
tonic-clonic seizures (1 paper, 2021).
undifferentiated carcinoma (1 paper, 2018). A usually aggressive malignant epithelial neoplasm composed of atypical cells which do not display evidence of glandular, squamous, or transitional cell differentiation. "Histologically, most cases (31; 89%) were adenocarcinoma, but there were 2 cases of undifferentiated carcinoma and one case of somatostatin-producing tumour." (PMID 30308425, 2018).
Vestibular schwannoma (1 paper, 2009). A vestibular schwannoma (also known as acoustic neuroma, acoustic neurinoma, or acoustic neurilemoma) is a benign, usually slow-growing tumor that develops from the VIIIth cranial nerve supplying the inner ear. "Vestibular schwannoma is a benign cerebellopontine angle tumor and it expresses various hormone receptors for examples estrogen, progesterone, androgen, somatostatin and glucocorticoid." (PMID 19889208, 2009).
tumor (296 papers, 1994 to 2026). "Approved [68 Ga]-SST radiopharmaceuticals are routinely used for diagnostic PET/CT imaging to assess SST-expressing tumor burden and to assess eligibility for targeted therapy with the approved SST-targeted [177Lu]Lu-DOTATATE." (PMID 38581469, 2024). "SSTR1 hypermethylation has been detected in 64% of HNSCC samples and has also been associated with tumor extent, disease stage, SST hypermethylation, and increased expression of galanin (GAL), GALR2, TAC1, and tachykinin type 1 receptor (TACR1)." (PMID 36769317, 2023). "The purpose of the next section of this review is to discuss the role of SST and its analogs with receptor-specific biological functions associated in different type of tumours." (PMID 38203605, 2023). "These tumour suppressor activities of SST are linked to cytotoxic and cytostatic effects, induction of CDKs and, importantly, apoptosis in normal and malignant cells via direct action of SSTR subtypes in a receptor-specific manner." (PMID 38203605, 2023). "Many studies have failed to report SSTRs’ expression in pancreatic adenocarcinoma, which is directly related to the loss in tumour growth regulation by using SST or its analogues." (PMID 38203605, 2023). "In these tissue samples, it was shown that tumor-specific hypermethylation of the SST promotor was associated with reduced SST mRNA expression levels." (PMID 33085037, 2021). "The activation of Sstr3 by somatostatin/SSAs or its overexpression has been associated with the induction of apoptosis in various normal and tumor cells." (PMID 34205778, 2021). "Hypermethylation of the SST gene (encoding somatostatin) and concomitant downregulation of its expression were found to be common in tumor entities, representing a promising pan‐cancer biomarker." (PMID 32243066, 2020). "Here we analysed the therapeutic potential of an innovative biohybrid consisting of the tumor-associated peptide somatostatin and the photosensitizer ruthenium in AML cell lines and primary AML patient samples." (PMID 31941913, 2020). "Next, we showed expression of mRNA encoding SST and its receptors is present in matched normal and tumor tissue samples." (PMID 27927191, 2016). "Methylation of SST was associated with several clinicopathologic factors, including tumor size (P = 0.043), stage (P = 0.008), GALR2 methylation (P = 0.041), TAC1 methylation (P = 0.040), and DAPK methylation (P = 0.012) (Table 1and S1 Table)." (PMID 25734919, 2015). "In particular, the use of SST analogs as radiolabeled peptides is a powerful diagnostic tools for in vivo tumor imaging, since, after intravenous injection they accumulate in SST receptor-expressing tumors." (PMID 23476673, 2013). "Moreover, tumor‐associated macrophages (TAMs) express SSTRs,37 and somatostatin has been shown to inhibit monocyte chemotaxis." (PMID 40789673, 2025). "Low SST tissue expression suggests loss of the inhibitory role of SST in tumor growth." (PMID 38540191, 2024). "SSTR subtypes are the potential target of SST analogs to elicit multiple functions, including antiproliferative effect also exerting inhibitory role in angiogenesis and inhibition of several other downstream signaling pathways associated with tumour growth." (PMID 38203605, 2023). "Whether somatostatin expression is linked to tumor proliferation or progression remains unclear, especially because its main function is essentially antiproliferative." (PMID 35566491, 2022). "In the current approach we analysed the AML targeting potential of an innovative biohybrid consisting of the tumor-associated peptide somatostatin and the photosensitizer ruthenium using molecularly and cytogenetically fully annotated primary AML patient samples as targets." (PMID 31941913, 2020).
tumor (continued). "In the current approach, we analysed the AML targeting potential of an innovative biohybrid consisting of the tumor-associated peptide somatostatin and the photosensitizer ruthenium using molecularly and cytogenetically fully annotated primary AML patient samples." (PMID 31941913, 2020). "What is the molecular mechanism underlying tumor imaging using SST antagonists?" (PMID 30232095, 2018). "In marked contrast, HF-fed SST-KO mice exhibited much higher tumor incidence than LF-fed SST-KO mice, which could be associated with higher mammary complexity." (PMID 26956474, 2016). "These tumors may secrete excessive quantities of hormone such as gastrin, insulin, vasoactive intestinal polypeptide (VIP), glucagon, or somatostatin and may be associated with distinct clinical syndromes, with approximately one third of these neoplasms becoming clinically apparent." (PMID 31263451, 2019). "Indeed, the possible dissociation between tumor shrinkage and biochemical control has been described and may suggest different mechanisms underlying antimitotic and antisecretory actions of somatostatin analogues." (PMID 22574156, 2012). "The growth hormone-releasing inhibiting peptide/somatostatin (SST/SRIF) system is an interesting system involved in the interactions between tumor cells and other TME cells in CRC." (PMID 40508145, 2025). "Targeting the somatostatin/cortistatin-system is considered a successful avenue for treating different tumour pathologies." (PMID 40268793, 2025). "Clinical research has indicated that elevated SST methylation levels in the serum of CRC patients can predict tumor recurrence and cancer-related mortality." (PMID 39949372, 2025). "In cases of unresectable or metastatic disease, treatment focuses on tumor stabilization and palliation of symptoms by reducing somatostatin secretion." (PMID 40647278, 2025). "One of the effects of the anti-tumor activity of the SRIF/SST system in CRC is the interaction between cancer cells and other TME cells." (PMID 40508145, 2025). "In vivo SSTR2 transfer into human PDAC tumors strongly inhibited tumor growth and progression by inducing intra-tumoral production of SST." (PMID 40134804, 2025). "Selective downregulation of SST2 expression in corticotroph tumor cells by high cortisol levels is thought to impair the efficacy of SST2 preferring somatostatin analogs in the treatment of CD." (PMID 40452800, 2025). "A combination of LHRH with somatostatin reduced tumor growth by 50–60% in both tumor models, while alone, AnN-201 was not so effective." (PMID 41465311, 2025). "SST exerts direct anti-tumor effects by direct binding to and activation of one or more of five different SST receptors (SSTR1-5), with SSTR2 representing an inhibitory G protein-coupled receptor." (PMID 40134804, 2025). "Whereas the ectopic ACTH-secreting tumours express the cell-surface receptors for somatostatin, 111In-pentetreotide (OCT) scintigraphy is often chosen as confirmatory exam." (PMID 39347909, 2025). "Complete tumor removal results in the normalization of somatostatin levels, thereby alleviating its broad inhibitory effects on gastrointestinal and pancreatic functions." (PMID 40647278, 2025). "In vitro evaluation of 61Cu- and 68Ga-labeled SST analogues was performed in SSTR positive AR42J tumor cells." (PMID 39909885, 2025). "Another strategy that is currently under investigation is the upregulation of SST, as the cytotoxicity of PRRT strictly depends on SST density on the surface of tumor cells." (PMID 38581469, 2024). "Many studies have demonstrated the tissue expression of SST (mRNA, protein) and characterized the cells producing SST in this type of tumor." (PMID 38540191, 2024). "A lengthening of the waiting list (182 [IQR 100–357] vs. 60 days, p < 0.001) and increased use of anti-tumor medical treatments (any therapy, peptide receptor radionuclide therapy, and somatostatin analogs; all p < 0.001) was found." (PMID 39033485, 2024).